EZR (ezrin)
Diseases named in the same sentence as EZR in open-access papers (continued):
Sharing a sentence is not in itself a finding about the gene and the disease.
breast carcinoma (continued). "Direct links between ezrin and hormone receptor signalling in breast cancer have been reported in vitro previously; in particular, links between ezrin activation following 17β‐oestradiol (E2) treatment have been observed." (PMID 36938826, 2023). "Ezrin was present in all breast cancer cell lines tested, with the highest relative levels in TN/basal-like MDA-MB-231 and MDA-MB-468 cells, and HER2+ SK-BR-3 cells." (PMID 36923551, 2022). "Next, ROC curves and the area under the curve (AUC) were used to assess the accuracy of AJAP1 and Ezrin expressions as biomarkers for breast cancer diagnosis." (PMID 35311087, 2022). "Ezrin was lowest in TN/basal or normal-like breast cancer cases within TCGA dataset, consistent with the TMA analysis." (PMID 36923551, 2022). "In this study, we show that upregulating or downregulating ezrin expression modifies the sensitivity of breast cancer cells to doxorubicin and docetaxel treatment in vitro and is associated with changes in PI3K/Akt and NFκB pathway activation." (PMID 36923551, 2022). "In breast cancer, Ezrin also plays an instrumental role in mediating tumor progression and metastasis." (PMID 35311087, 2022). "Of the nine MRGs, EZR is an oncogenic gene with a well-documented role in cell adhesion and cell migration, but it has rarely been investigated in breast cancer." (PMID 37304008, 2022). "In this work, we presented a new finding on hyaluronan synthase 2 (HAS2) and the related membrane cytoskeletal cross linker protein, Ezrin, on antiestrogen resistance of receptor-positive (ER+) breast cancer cells." (PMID 36386154, 2022). "Here, we provide evidence that ezrin inhibition sensitizes metastatic breast cancer cells to anthracycline and taxane treatment both in vitro and in vivo." (PMID 36923551, 2022). "For example, adipokines such as LEP and RETN promote metastasis through activation of ezrin, radixin and moesin proteins in breast cancer cells." (PMID 36362348, 2022). "AJAP1 and Ezrin expressions were detected in 377 cases of breast cancer using immunohistochemistry (IHC) technology." (PMID 35311087, 2022). "Collectively, these observations suggest that ezrin is the predominant ERM protein involved in modulating chemosensitivity of breast cancer cells to these cytotoxic drugs." (PMID 36923551, 2022). "We then looked for correlations between NSC sensitivity and expression levels of ezrin and radixin in this panel of breast cancer cells." (PMID 36923551, 2022). "In summary, the data we present here demonstrate the potential of anti-ezrin therapy at targeting metastatic breast cancer cells in combination with chemotherapy and provide rationale for testing its efficacy in other cancer types." (PMID 36923551, 2022). "To explore the relationship between ezrin expression and cancer cell sensitivity to chemotherapy agents, we began by assessing ezrin levels in a panel of breast cancer cell lines by immunoblotting." (PMID 36923551, 2022). "Taken together, our findings demonstrate the impact of anti-ezrin treatment in modulating response to chemotherapy in breast cancer cells as well as the efficacy of anti-ezrin treatment in combination with chemotherapy at reducing metastatic burden." (PMID 36923551, 2022). "In our current analyses, we found EZR to be the most abundantly expressed ERM family member across all breast cancer cases in TCGA cohort." (PMID 36923551, 2022). "To extend these observations in clinical samples, we assessed ezrin mRNA and protein expression in primary breast cancer cases using TCGA breast cancer dataset (n = 1,082) and a locally accrued TMA cohort (SEOBC, n = 347), respectively." (PMID 36923551, 2022). "The nontumorigenic MCF10A breast epithelial cell line expressed lower ezrin levels than all tested breast cancer cell lines." (PMID 36923551, 2022).
breast carcinoma (continued). "Using in vitro cell line models, we show that upregulating or downregulating ezrin decreased or increased, respectively, the sensitivity of breast cancer cells to doxorubicin (DOX) and docetaxel (DTX) treatment." (PMID 36923551, 2022). "As an important regulator of metastasis, ezrin and its association with PODXL has recently been explored in breast cancer extravasation." (PMID 34201212, 2021). "Ezrin phosphorylation regulates the invasion and metastasis of breast cancer cells and pancreatic cancer cells, and radixin regulates cell migration and cell-cell adhesion in prostate cancer." (PMID 33833821, 2021). "EZR, which has been reported to be overexpressed in human cancers, such as breast cancer and colorectal cancer, is significantly upregulated in PC tissues." (PMID 34627255, 2021). "Intriguingly, ezrin regulates the expression of angiogenic factors in both macrophages as well as tumor cells, as ezrin knockdown in breast cancer cells reduces the macrophage expression of VEGFA and MMP9 mRNAs." (PMID 33086476, 2020). "The role of macrophage ezrin in chemoattraction towards breast cancer cells was determined by trans-well migration assay." (PMID 33086476, 2020). "Recent study unraveled the importance of ezrin protein acetylation in CCL18-elicited breast cancer metastasis." (PMID 32647287, 2020). "We investigated the influence of macrophage ezrin on the release of factors that induce the migration and invasion of breast cancer cells." (PMID 33086476, 2020). "We identified a juxtamembrane positively charged cluster responsible for the interaction of MT1-MMP with ERM (ezrin/radixin/moesin) cytoskeletal connectors in breast carcinoma cells." (PMID 32028690, 2020). "The ezrin knockdown of THP-1 cells substantially reduced the M2 CM-stimulated clonogenic growth of both breast cancer cell lines." (PMID 33086476, 2020). "In this connection, a number of clinical studies have highlighted that ezrin is involved in tumor progression, especially metastasis, in osteosarcoma, lung cancer, tongue squamous cell carcinoma, breast cancer, pancreatic cancer, and uterine cervical cancer." (PMID 31936668, 2020). "We observed that the chemoattraction and matrigel invasion of both breast cancer cell lines toward M2 CM from ezrin-depleted THP-1 cells was markedly reduced compared to control M2 CM." (PMID 33086476, 2020). "Ezrin expression in breast cancer, endometrial cancer, uterine cancer, uveal melanoma (Ilmonen, Vaheri, Asko‐Seljavaara, & Carpen, 2005), and soft tissue sarcoma (Weng, Ahlén, Aström, Lui, & Larsson, 2005) is associated with low survival rate." (PMID 32281236, 2020). "Accordingly, a recent promising work on a mouse model of breast cancer has shown that systemic treatment with an ezrin inhibitor reduces the migration of cancer cells, also diminishing the metastatic burden to the axillary lymph nodes and the lungs." (PMID 31936668, 2020). "For instance, ezrin inhibition reduced metastatic spread of OS and breast cancer, while silencing moesin and radixin were shown to reduce migration and invasion of melanoma and colon cancer, respectively." (PMID 33005093, 2020). "CM from both breast cancer cell lines increased the expression of both transcripts, and ezrin depletion inhibited the stimulus-dependent expression of MMP9 mRNA in both cell lines, and VEGFA mRNA expression in MCF-7 cells." (PMID 33086476, 2020). "Ezrin mediates cell migration and invasion in lung and breast cancers that can be inhibited by the overexpression of miR-183." (PMID 33240887, 2020). "Similar to observations in other carcinomas, Ezrin is elevated in breast carcinoma and ovarian carcinoma." (PMID 33240887, 2020). "Clinically, ezrin overexpression has also been reported to correlate with the presence of lymph node metastasis in breast cancer, pancreatic cancer, and nonsmall-cell lung cancer." (PMID 30678714, 2019).
breast carcinoma (continued). "EZR mRNA expression level in tumor tissue was significantly upregulated compared to that of normal breast tissue of breast cancer patients (P < 0.05)." (PMID 31452341, 2019). "A similar mechanism was reported in pancreatic and breast cancer, where the upstream signal involved in ezrin-mediated NF-κB activation involved β1-integrin." (PMID 31455004, 2019). "In a patient study, the ezrin expression was upregulated, while that of E-cadherin was decreased in breast cancer as compared to the control specimen." (PMID 31261642, 2019). "We have previously shown that ezrin knockdown in breast cancer cells leads to reduced lymphangiogenic activity in a Matrigel plug xenograft model in mice." (PMID 30678714, 2019). "The anti-tumour effects of the plant substrate 15α-MP against glioblastoma and breast cancer progression are suggested to be mediated the modulation of Stat3, CyclinB1, Alk, ezrin, merlin, and Erk1/2 functions." (PMID 31382374, 2019). "The ezrin protein expression was positive with uniform brown‐yellow granules in the cell membrane, cavity surface and cytoplasm of the breast cancer cells." (PMID 31452341, 2019). "Survival analysis of the present work showed that high expression of EZR mRNA was correlated with poor overall survival of the breast cancer patients." (PMID 31452341, 2019). "Ezrin, LaminA/C, cleaved caspase‐3, Bcl‐2, and Bax protein expressions in tumor tissues and para‐carcinoma tissues of breast cancer patients were detected via Western blotting." (PMID 31578772, 2019). "Ezrin expression was negatively correlated to the E-cadherin expression in a subpopulation of breast cancer patients with a high expression of ezrin [ezrin(high)] and a low expression of E-cadherin [E-cad(low)]." (PMID 31261642, 2019). "In conclusion, EZR mRNA was upregulated in breast cancer which was in accordance with its coding protein (ezrin) expression pattern detected by immunohistochemistry assay." (PMID 31452341, 2019). "Ezrin protein (coded by EZR) expression was also examined by immunohistochemistry assay in 120 breast cancer patients." (PMID 31452341, 2019). "High expression of EZR mRNA was correlated with poor overall survival (OS) of the breast cancer patients (HR = 1.40, P = 0.038)." (PMID 31452341, 2019). "To further investigate the role of the EZR gene in the development of breast cancer, we constructed the protein‐protein network by STRING to identify the interaction between the relevant genes." (PMID 31452341, 2019). "We found that the EZR gene was upregulated in cancer tissue compared to normal breast tissue in breast cancer patients." (PMID 31452341, 2019). "Ezrin is the most studied member of the family, it is expressed in epithelial cells and its overexpression has been reported in breast cancer, prostate cancer, hepatocellular carcinoma, ovarian cancer, and endometrial cancer." (PMID 29587669, 2018). "It has been reported that when Ezrin was silenced, CCL5 induced cell motility and invasiveness was also inhibited indicating the potential role for Ezrin in the process of CCL5 induced breast cancer cell metastasis." (PMID 30224826, 2018). "We demonstrated that Syk phosphorylates ezrin in a direct manner on its Tyr424 residue and that both proteins colocalize in the plasma membrane ruffles in breast cancer cells." (PMID 28306714, 2017). "The same ezrin phospho-peptide was the only one identified in the Syk-positive breast cancer cells in the MDA231 dataset." (PMID 28306714, 2017). "Oestradiol enhanced breast cancer cell motility and invasion via extranuclear activation of actin-binding protein ezrin." (PMID 28717394, 2017). "Ovarian and breast carcinomas share the ability to disseminate by forming malignant effusions, and we therefore sought to compare the role of ezrin and p130cas in these tumors." (PMID 27622508, 2016).
breast carcinoma (continued). "Our previous studies in EVs shed from multidrug resistant breast cancer cells showed a selective packaging of Ezrin, Radixin, Moesin and CD44 in resistant breast cancer cell-derived EVs." (PMID 26938523, 2016). "We previously compared the gene expression profiles of primary breast carcinomas and breast carcinoma effusions, and found ezrin and p130Cas to be upregulated in effusion specimens at the mRNA and protein level." (PMID 27622508, 2016). "Ezrin is a cytoskeleton and signaling molecule that regulates cell adhesion, migration, and invasion, whereas Akt2 is a kinase involved in invasiveness of breast cancer cells and is able to phosphorylate ezrin." (PMID 27314390, 2016). "Even though these effects seem to be specific to the inactivation of ezrin and radixin in breast cancer cells, it is likely that inactivation of ErbB-mediated signaling contributes only partially to this mechanism." (PMID 27029001, 2016). "Either inhibition of c-Src and PKCα or knock-down of ezrin blocked resistin-induced breast cancer cells invasion." (PMID 26729407, 2016). "We previously reported on overexpression of both ezrin and p130Cas in breast carcinoma effusions compared to primary carcinomas." (PMID 27622508, 2016). "Ezrin Y145 phosphorylation in mouse mammary carcinoma cell line SP1 and in pig kidney epithelial LLC-PK1 cells resulted in cell spreading." (PMID 26983550, 2016). "In contrast to HeLa cells, SKBR3 cells showed no expression of moesin, and we therefore focused on the presumed role of ezrin and radixin in the regulation of ErbB2 receptors in this breast cancer cell line." (PMID 27029001, 2016). "A previous study from our group found that in breast carcinoma effusions both ezrin and p130Cas were significantly overexpressed compared to primary carcinomas." (PMID 27622508, 2016). "In a subsequent in vitro study, both ezrin and p130Cas mediated the growth of anchorage-independent breast carcinoma cells as 3-dimensional spheroids that were used as a model for breast carcinoma metastasis." (PMID 27622508, 2016). "It was reported that high ezrin expression levels play a role in promoting invasion and metastasis of esophageal carcinoma, breast cancer, ovarian cancer, liver cancer, osteosarcoma, and other common tumors." (PMID 25929323, 2015). "In breast cancer cells, the co-expression and interaction of EZR and PODXL increases the metastatic potential of the cells." (PMID 26135398, 2015). "As ezrin is a key regulator of Src activity, we examined the potential role of Src/ezrin in tumour-induced angio/lymphangiogenesis in breast cancer." (PMID 25231728, 2014). "The effects of ezrin knockdown and mutation on angio/lymphangiogenic potential of human MDA-MB-231 and mouse AC2M2 mammary carcinoma cell lines were examined in the presence of constitutively active or wild-type (WT) Src." (PMID 25231728, 2014). "Estrogens stimulate ER+ breast cancer cell movement through the ezrin–radixin–moesin family of actin regulatory proteins, inducing actin and cell membrane remodeling." (PMID 24904530, 2014). "Ezrin Y477, a Src substrate, is required for the Src-induced invasive phenotype in breast cancer cells." (PMID 25231728, 2014). "Further studies are required to elucidate the role of the Src/ezrin pathway in the invasion process and its potential as a novel prognostic/predictive biomarker for early-stage metastatic phenotype in breast cancer." (PMID 25231728, 2014). "Our results identify a direct requirement for ezrin in Src-induced VEGF-C expression in breast carcinoma cells." (PMID 25231728, 2014). "It represses the expression of EGR1 and functions as an oncogene in breast cancer, but it also targets the Ezrin gene and inhibits cell migration in T47D cells." (PMID 25394902, 2014). "The results describe a novel function for ezrin in the regulation of tumour-induced angio/lymphangiogenesis promoted by Src in breast cancer." (PMID 25231728, 2014).
breast carcinoma (continued). "A trend of association between high ezrin expression and positive LN status was also suggested in our TMA analysis and is currently being validated in a larger breast cancer cohort." (PMID 25231728, 2014). "In order to assess the role of ezrin in Src-mediated angio/lymphangiogenesis, we utilized the human breast carcinoma MDA231 cell line expressing constitutively active pWZL-hygro-Y527F Src (MDASrc)." (PMID 25231728, 2014). "Our results suggest that a positive correlation exists between high ezrin expression and LVI in breast cancer, providing a rational for the presence of LN metastasis in tumours with high ezrin expression." (PMID 25231728, 2014). "Ezrin was shown to be selectively packaged in both leukaemic and breast cancer-derived MPs relative to their donor cells." (PMID 23593486, 2013). "To investigate the role of ezrin and p(T567)-ezrin in breast cancer invasion, we assessed their expression and distribution in human breast cancer tissues." (PMID 24086451, 2013). "Ezrin was present in both leukaemic and breast cancer-derived MPs, where it was selectively packaged relative to the donor cells." (PMID 23593486, 2013). "Ezrin is an indispensable factor for tumor cell metastasis in osteosarcomas, breast cancer, nasopharyngeal carcinomas, and prostatic cancer." (PMID 23357878, 2013). "E2 enhanced breast cancer cell motility and invasion via extranuclear activation of actin-binding protein ezrin." (PMID 24222765, 2013). "Altogether, these findings implicate a pivotal regulatory role of the Src phosphorylation site, Y477, on ezrin in invasion and dissemination of breast cancer cells." (PMID 22397367, 2012). "In this report, we show for the first time that Y477F ezrin attenuates local invasion and distant metastasis of breast carcinoma cells transplanted into the orthotopic site of recipient mice." (PMID 22397367, 2012). "In the present study, we show for the first time that a single tyrosine-to-phenylalanine substitution (Y477F) in ezrin markedly attenuates local invasion and distant metastasis of breast cancer cells from the primary tumor site." (PMID 22397367, 2012). "Recent findings indicate that ezrin is required for metastasis of breast carcinoma, osteosarcoma and HGF-induced rhabdomyosarcoma." (PMID 22629406, 2012). "Since cell migration is an important early step in tumor invasion, we examined the role of Y477 ezrin on migration function of a highly metastatic carcinoma variant cell line, AC2M2, derived from the mouse mammary tumor cell line, SP1." (PMID 22397367, 2012). "In this study, we investigate the effects of 17β-estradiol (E2) on the activation of ezrin and its role in estrogen-dependent breast cancer cell movement." (PMID 21818323, 2011). "Notwithstanding, evidence on the link between moesin and clinical feature of cancer is limited, while more clinical trials focus on the role of ezrin in different types of cancer progression, including in breast cancer." (PMID 21818323, 2011). "It has been reported that ezrin silencing by small hairpin RNA or the expression of dominant-negative amino-terminal ezrin reverses metastatic behaviors of human breast cancer cells." (PMID 21818323, 2011). "The key finding of the present manuscript is that estrogen signals to ezrin and induces its phosphorylation, which contributes to the enhanced ability of ER+ breast cancer cells to migrate and invade the surrounding environment." (PMID 21818323, 2011). "In T47-D breast cancer cells, E2 rapidly enhances ezrin phosphorylation at Thr567 in a time- and concentration-dependent manner." (PMID 21818323, 2011). "The actin binding protein ezrin is a key component in tumor metastasis and its over-expression is positively correlated to the poor outcome of breast cancer." (PMID 21818323, 2011). "Others found that overexpression of miR-183 inhibited migration and invasion of lung cancer and breast cancer cells, by targeting the protein ezrin." (PMID 21920043, 2011).